OCLN (occludin)
Diseases named in the same sentence as OCLN in open-access papers (continued):
Sharing a sentence is not in itself a finding about the gene and the disease.
ischemia (continued). "Multifluorescence immunostainings for the tight junction protein claudin-5 and occludin (in areas of ischemia-induced vascular damage) revealed decreased surface expression of claudin-5 and occludin in VEGF-LOF." (PMID 35175562, 2022). "A previous study has indicated that increased serum occludin levels are a potential marker of BBB damage during ischemia and reperfusion following an arterial ischemic stroke." (PMID 33532130, 2021). "The activity of MMP9 and MMP2 can break down the BBB via directly degrading tight junction proteins such as occludin and claudin-5, leading to reversible degradation early after the onset of ischemia and initiating vasogenic edema." (PMID 32221863, 2021). "We reported that increased endothelial permeability following ischemia reflects alterations in organization of tight/adherens junctional (TJs/AJs) proteins (e.g. occludin, claudins, VE-cadherin, catenins)." (PMID 33348090, 2021). "Mounting evidence indicates that the increased permeability of BBB induced by ischemia generally correlates with the alterations of ZO-1, claudin-5, and occludin." (PMID 32256351, 2020). "Our results demonstrated that ischemia-induced autophagy mediated the degradation of occludin and that inhibition of autophagy by 3-MA reversed occludin degradation and attenuated BBB dysfunction." (PMID 32169114, 2020). "Here, we have demonstrated that ischemia-induced autophagy occurs in brain endothelial cells in vitro and rat brain capillaries in vivo and that this mediates the degradation of occludin, a major component of TJs in the BBB." (PMID 32169114, 2020). "Western blotting showed that QKL upregulated ZO-1, claudin-5, VE-Cadherin, and occludin, compared to the Ischemia group." (PMID 32908557, 2020). "The molecular mechanisms that mediate occludin modification and translocation to autolysosomes during autophagy-mediated degradation during ischemia remain to be elucidated." (PMID 32169114, 2020). "Injuries such as ischemia and traumatic brain injury lead to a disruption and reconstruction of ZO-1 and occludin and an increase in BBB permeability." (PMID 29925377, 2018). "In the sham group, occludin and CD31 signals were aligned almost perfectly, whereas in the vehicle-ischemia group the alignment became disorganized, with the occludin signal being greatly reduced, indicative of a damaged BBB." (PMID 28645333, 2017). "We recently reported that ischemia induced rapid degradation of tight junction protein occludin in cerebromicrovessels." (PMID 28079139, 2017). "Injuries such as ischemia and trauma lead to a disruption and reconstruction of ZO-1 and occludin, and an increase in BBB permeability." (PMID 25315906, 2014). "In a hypertensive rat model, induced ischemia causes increased MMP-2 secretion and degradation claudin-5 and occludin in endothelial tight junctions, leading to breakdown of the blood-brain barrier." (PMID 25412440, 2014). "Postoperative ischemia, the release of inflammatory factors, or surgical trauma can directly damage the intestinal epithelial cells and intercellular tight junctions (e.g., ZO-1 and occludin protein), leading to mucosal damage." (PMID 40977969, 2025). "Besides, the pre-ischemic overexpression of RFC1 partially rescued collagen-4 and occludin levels which would be decreased after ischemia." (PMID 37328777, 2023). "CAY10444 rescued the decreased expression of the tight junction (TJ) proteins zonula occludens 1 (ZO1) and occludin after ischemia induced by transient MCAO (tMCAO) and reduced the increase in aquaporin 4 (AQP4) levels after tMCAO, preserving the integrity of the BBB." (PMID 35685645, 2022). "Although differences of the occludin expression were not detectable at the level of fluorescence microscopy, lower protein levels of occludin were observed in ischemia-affected striatal areas (p = 0.029; n = 6) when compared to the contralateral control regions." (PMID 30744693, 2019).
ischemia (continued). "Furthermore, occludin and ZO-1 down-regulation under ischemia suggested that miR-381-3p plays a role in regulating epithelial barrier function." (PMID 29540663, 2018). "However, in the Sac-1004-ischemia group, a certain degree of rescue of the superimposed lining of occludin and CD31 was observed, suggesting that the BBB destruction after I/R was attenuated." (PMID 28645333, 2017). "Of note, although reperfusion further increased the levels of each occludin fragments, the overall trend of changes over ischemic duration was similar for rats with or without reperfusion (compare before (Pre) vs. after (Post) ischemia data in the figure)." (PMID 28079139, 2017). "Furthermore, blood occludin levels remained significantly higher than its basal level within the first 24 hours after ischemia onset." (PMID 28079139, 2017). "In addition, the administration of PPUS significantly reduced brain edema and rescued ischemia-induced ZO-1 and occludin disruption, suggesting that PPUS regulates BBB integrity through tight junction proteins." (PMID 26012470, 2015). "The levels of occludin and ZO-1 were measured to elucidate whether SC-51089 reduces degradation of these TJPs in response to ischemia." (PMID 26648273, 2015). "The findings of this study reveal a beneficial effect by IVIg on ischemia-induced leukocyte recruitment as well as on endothelial permeability (mediated by tight-junction proteins claudin 5 and occludin), as well as an anti-apoptotic effect on endothelial cells mediated by Bcl-2 and Bcl-XL." (PMID 24991401, 2014). "The data indicated that early exercise significantly inhibited the ischemia-induced reduction of occludin, and an increase in MMP-9 promoted TIMP-1 expression (p < 0.01), attenuated the BBB disruption (p < 0.05) and neurological deficits (p < 0.01) and diminished the infarct volume (p < 0.01)." (PMID 23708107, 2013). "The expression level of occludin has been reported to decrease in ischemia." (PMID 23094016, 2012). "In detail, post-translational modification of tight junctions in response to ischemia may activate vascular endothelial growth factor, Rho/ROCK, and cyclic AMP/PKA, causing phosphorylation of tight junction proteins (occludin, claudin-5, and ZO-1) and thus increasing BBB permeability." (PMID 33551950, 2020). "Cerebral ischemia induced a time-dependent increase of blood occludin with a sharp increase at 4.5-hour post-ischemia onset, which concurrently occurred with the loss of occludin from ischemic cerebral microvessels and a massive BBB leakage at 4.5-hour post-ischemia." (PMID 28079139, 2017). "Alternatively, as the epithelium becomes apoptotic, occludin, E-cadherin, and mucin 13 may be internalized and subsequently degraded, possibly aided by lactic acid build up and reduced intracellular pH during ischemia." (PMID 24805256, 2014). "IF staining analysis revealed a significant reduction in the average fluorescence intensity of Claudin-5, Occludin, and ZO1 after ischemia induction compared to the sham group." (PMID 40365318, 2025). "In this study, we found that chronic stress induced intestinal artery contractions, leading to ischemia, hypoxia, decreased ATP5D expression and ATP production, and low occludin expression." (PMID 36003517, 2022). "3-MA administration restored the decrease in the occludin I/C ratio in MCAO rats, indicating that autophagy mediates the degradation of occludin during ischemia." (PMID 32169114, 2020). "Immunofluorescence staining and western blot analysis of ZO-1, Occludin and JAM-A further demonstrated that adjudin preserved BBB integrity in ischemia/reperfusion injury models." (PMID 24927761, 2014). "Similar findings have been reported in a non-pregnant animal model of ischemia/reperfusion, as tight junction proteins claudin-5 and occludin were found to be unchanged in the brain capillaries of mice subjected to kidney ischemia/reperfusion." (PMID 37569342, 2023).
ischemia (continued). "Unlike occludin, claudin-5, and ZO-1, which rapidly decreased early after ischemia, tricellulin remained expressed until 6 h after ischemia before gradually declining." (PMID 36806348, 2023). "There was no significant change in ZO-1 expression (a tight junction protein modulated by MMP-9) between control and cKO mice in response to 2h-ischemia/4h-reperfusion, indicating the critical role of MMP-2/occludin pathway in neuronal ZnT3-modulaed BBB disruption in response to cerebral ischemia." (PMID 37962463, 2023). "Additionally, the morphology of TJ components identified by antibodies against occludin and claudin-5 appears to be regularly maintained in regions where FITC-albumin massively leaked into the neuropil 25 h after ischemia." (PMID 26834557, 2016). "Delayed rt-PA treatment enhances the fragmentation of occludin and claudin-5 24 h after middle cerebral artery (MCA) occlusion in rats, and reduces claudin-5 at 24 h or occludin and ZO-1 at 48 h after ischemia in mice." (PMID 26834557, 2016). "In support of this idea, the tight junctional protein occludin was decreased by ischemia and preserved by glucose, but not doxycycline or GM 6001." (PMID 24805256, 2014). "In contrast, after ischemia, lubiprostone resulted in a large, significant increase in TER, decrease in 3H-mannitol fluxes, a major return of occludin to detergent-insoluble fractions (lane 2 and 3) comparable to control and a large, significant increase in Isc." (PMID 22553939, 2012). "Neither ischemia nor fingolimod changed the expression of the tight junction protein occludin." (PMID 31165772, 2019). "Although slightly decreased protein levels of occludin were found in ischemia-affected striatal areas, these alterations could not be captured at the level of fluorescence microscopy." (PMID 30744693, 2019). "Here our data showed that blocking β2-AR significantly inhibits ischemia-induced BBB damage through suppressing HIF-1α expression and occludin degradation, indicating that β2-AR-HIF-1α signaling may represent promising therapeutic targets for preventing ischemia-induced BBB damage." (PMID 28855859, 2017). "Occludin and E-cadherin can be degraded by MMPs; however, MMP inhibition did not curtail occludin or E-cadherin destruction, implying MMPs are not responsible for their reduction following ischemia." (PMID 24805256, 2014).
Sepsis (54 papers, 2012 to 2026). Sepsis is defined as life-threatening organ dysfunction caused by a dysregulated host response to infection. "Pre-clinical studies of sepsis demonstrate increased permeability is associated with upregulation of jejunal claudin-2 and claudin-5, along with downregulation of occludin and JAM-A." (PMID 40098052, 2025). "Importantly, our findings in sepsis revealed that Piezo1-deficient mice maintained the expression of pivotal TJ proteins (ZO-1 and occludin) that are crucial for the integrity of the intestinal mucosal barrier." (PMID 38575957, 2024). "Moreover, p38/ERK-mediated proteolytic disorganisation of occludin and VE-cadherin and endothelial cell apoptosis have also been implicated in the pathogenesis of sepsis-induced pulmonary vascular leakage." (PMID 37978525, 2023). "Further, in light of pre-clinical studies demonstrating alterations in occludin levels following sepsis, mice with occludin knocked out specifically in their intestinal epithelium were compared to wild-type mice after intra-abdominal sepsis." (PMID 40098052, 2025). "The qPCR results demonstrated that, in comparison to the control group, the sepsis group exhibited a significant increase in the expression of inflammatory factors, accompanied by a notable decrease in the expression of occludin (**P<0.01)." (PMID 40822580, 2025). "Immunohistochemical staining revealed that the expression levels of occludin were notably decreased in the sepsis group compared to the control group (*P<0.05)." (PMID 40822580, 2025). "Herein, we found that acute abdomen III lowered the endotoxin, D-lactate, and DAO levels in sepsis, and also enhanced the expressions of tight junction proteins (ZO-1, claudin-1, and occludin), which were crucial in maintaining intestinal epithelial integrity." (PMID 40582762, 2025). "In summary, acute abdomen III reduced sepsis-induced inflammation, thereby promoting the levels of ZO-1, claudin-1 and occludin, which implied its role in protecting intestinal barrier function." (PMID 40582762, 2025). "Within functional analyses, the deletion of claudin-2 reduced gut permeability and attenuated intestinal inflammation, whereas an occludin blockade exacerbated gut hyperpermeability with increased bacteremia during sepsis." (PMID 40284216, 2025). "After treatment with S. boulardii (CNCM I-745), the inflammatory damage with sepsis was reduced, and the expression level of occludin was significantly increased." (PMID 40822580, 2025). "In a murine model following cecal ligation and puncture surgery, sepsis induction led to increased claudin-2 expression and decreased occludin expression." (PMID 40284216, 2025). "The integrity of the intestinal barrier, assessed by the expression of the tight junction proteins ZO-1, Occludin, and Claudin-5, was compromised in the sepsis group but was preserved by the ghrelin and Fer-1 treatment." (PMID 39857660, 2024). "In a study involving 51 sepsis patients, plasma levels of occludin (OCLN), claudin-5 (CLDN-5), zonula occludens-1 (ZO-1), PCT, and lactate were evaluated." (PMID 39201697, 2024). "While the role of such combined approaches in thyroid cancer remains unexplored, atezolizumab (an anti-PD-L1 agent) increased the expressions of claudin-1 and occludin in murine ileum during sepsis." (PMID 39458944, 2024). "In a previous study, upregulation of SDC1 significantly restored occludin and ZO-1 expression in sepsis." (PMID 37614234, 2023). "Meanwhile, irisin upregulated occludin and ZO-1 in lung tissues of sepsis-induced acute lung injury rats." (PMID 38187112, 2023). "In human brain tissue samples from deceased patients with sepsis, a remarkable downregulation of TJ proteins (occludin, claudin-5 and ZO-1) was found in BMVECs, demonstrating impaired BBB integrity." (PMID 36817492, 2023). "In contrast, S100A9 KO significantly attenuated CLP sepsis-induced reduction of occludin and VE-cadherin levels in the lungs (n = 6)." (PMID 37978525, 2023).
Sepsis (continued). "In a study investigating the impact of berberine pretreatment on sepsis, occludin, ZO-1, and claudin-4 were found to exhibit decreased expression levels following CLP in rats." (PMID 38187112, 2023). "Compared with that in the sham group, the expression level of HIF-1α was significantly increased in the sepsis group (P < 0.05), and the expression levels of ZO-1, occludin and claudin-1 were significantly decreased (P < 0.05)." (PMID 35576220, 2022). "In sepsis‐induced lung injury, there is abnormal decrease in the expression of ZO‐1, Claudin 5, and Occludin, which are involved in lung vascular permeability." (PMID 36169256, 2022). "Quantitative analysis demonstrated that the staining intensity of occludin protein was significantly lower in sepsis group than in control group (P < 0.01), but was significantly higher in probiotics pretreatment group (P < 0.05)." (PMID 34536996, 2021). "The staining of occludin and ZO-1 proteins was significantly lighter in sepsis group than that of control group, and was stronger in pretreatment group than that of sepsis group but lighter than that of control group." (PMID 34536996, 2021). "Third, the tight junction-associated compounds, ZO-1 and occludin, and antiapoptotic gene expressions in lung tissues were significantly higher in the GLN-administered group, suggesting that sepsis-associated cell apoptosis and tissue injury were attenuated." (PMID 33223959, 2020). "As to tight junction genes, obesity with sepsis exhibited lower ZO-1 gene expression at 12 h, while occludin expression levels were lower at 12, 24, and 48 h after CLP compared to those of the SH group." (PMID 33223959, 2020). "In fatal sepsis, damaged BBB defined as a loss of cerebral endothelial expression of occludin is related with severe organ dysfunction and systemic inflammation." (PMID 32600371, 2020). "Mechanistically, claudin-2 and junctional adhesion molecule (JAM)-A are increased by sepsis, whereas claudin-5 and occludin are decreased by sepsis." (PMID 30923621, 2019). "Serum ZO-1, occludin, and zonulin are all elevated in sepsis; however, ZO-1 best stratified sepsis severity and degree of organ dysfunction." (PMID 30259344, 2018). "Collectively, these studies demonstrate that serum levels of ZO-1, occludin, zonulin, and claudin-5 are elevated in sepsis." (PMID 30259344, 2018). "The mRNA-levels of claudin-1, occludin and E-cadherin were significantly higher during sepsis, and septic animals curatively treated with anti-IL-6 did not display this increase in mRNA levels." (PMID 27044016, 2016). "Additionally, DYY inhibited inflammation (TNF-α, IL-1β, and IL-6), cell apoptosis, and promoted proliferation in sepsis, as well as the promotion of tight junction proteins (claudin-1, occludin, and ZO-1)." (PMID 41948377, 2026). "Notably, the treatment group exhibited significantly elevated expression of occludin in comparison to the sepsis group (*P<0.05)." (PMID 40822580, 2025). "Furthermore, the treatment group showed a significant reduction in the expression of inflammatory factors and a significant increase in the expression of occludin when compared to the sepsis group (**P<0.01)." (PMID 40822580, 2025). "Additionally, DHA has been shown to reduce blood-brain barrier permeability in a sepsis model by increasing the expression of the tight junction protein occludin (OCLN)." (PMID 39221152, 2024). "In addition, the ZO-1 and Occludin protein expressions were enhanced among sepsis + sphinganine mice, relative to the sepsis mice." (PMID 37292192, 2023). "In addition, the levels of ZO-1 and Occludin, the two major junction proteins, and that of the mucin protein Muc-1were significantly decreased in colon tissues of sepsis mice." (PMID 37081964, 2023). "They found that occludin and claudin-5 decreased due to sepsis." (PMID 38152336, 2023).